FANCA (FA complementation group A)
Diseases named in the same sentence as FANCA in open-access papers (continued):
Sharing a sentence is not in itself a finding about the gene and the disease.
anemia (23 papers, 2008 to 2026). A reduction in the number of red blood cells, the amount of hemoglobin, and/or the volume of packed red blood cells. "The FANCA gene, located on chromosome 16q24.3, encodes the Fanconi anemia complementation group A protein." (PMID 37623222, 2023). "This study was aimed to identify single nucleotide polymorphism of Fanconi anemia complementation group A (FANCA), associated with the rate of proliferation in uterine leiomyomas." (PMID 33202820, 2020). "However, the role of FA detoxification is strikingly relevant in cells with mutations in Fanconi anemia (FANCA) and in genes coding for the NER factors CSB and XPA." (PMID 38894680, 2024). "Our patient with SDHD developed PHEO and the other one with FANCA mutation was anaemia‐free." (PMID 39673085, 2024). "For the mild anemia phenotype, the underlying causal genetic factors could be attributed to the compound heterozygous mutations in FANCA gene (c.2832dup, p.Ala945CysfsTer6 and c.1902 T > G, p.Asp634Glu)." (PMID 36385762, 2022). "As for the anemia phenotype, the predicted benign missense mutation 1902 T > G could generate a small proportion of abnormally spliced isoform of FANCA." (PMID 36385762, 2022). "Our triplet links also include 60 genes known to be recurrently mutated or overexpressed in medulloblastoma, including OTX2, MYCN, the Fanconi anemia proteins FANCA and FANCI, and others." (PMID 41279093, 2025). "We also found that several Fanconi anemia (FA) proteins (e.g., FANCA, FANCF, FANCM, FANCD2), which are central proteins of inter-strand crosslink (ICL) repair, favored MMEJ." (PMID 38909016, 2024). "For the anemia phenotype, two rare mutations in the CDS of FANCA gene (NM_000135.4) were detected by trio-WES." (PMID 36385762, 2022). "Fanconi anemia (FANCA) genes, traditionally known for their essential roles in DNA repair and cytogenetic instability, have been demonstrated to be involved in meiosis and germ cell development." (PMID 33093844, 2020). "One interesting example, Fanconi anemia complementation group A (FANCA), a DNA repair protein, exhibited progressive apoptosis (progressive aplastic anemia) in knockout mice." (PMID 29116029, 2017). "Interestingly, we found that 10 of 11 patients with lymphoma and another solid tumor harbored germline mutations in Fanconi anemia complementation group (FANC) genes, including FANCI, FANCA, FANCG, FANCL, FANCD1, FANCF, FANCJ, and FANCS." (PMID 37546421, 2023). "To gain insight into the causes of EPO independence and tumorigenicity associated with loss of FANCA function, we performed whole-exome sequencing (WES) analysis of blasts isolated from the spleen of 5 TgSpi1FA+/+ and 9 TgSpi1FA−/− mice with anaemia and splenomegaly." (PMID 37573408, 2023). "FANCA is a Fanconi anemia complementation group (FANC) protein." (PMID 32962729, 2020). "The Fanconi anaemia proteins together with BRCA1/FANCS and BRCA2/FANCD1 act in a common pathway, FANCA/BRCA pathway, to coordinate the cellular response to DNA damage, driving DNA repair through homologous recombination (HR)." (PMID 36622663, 2023). "Furthermore, defects in this pathway caused by loss of FANCA could explain why FA patients suffer from iron overload and suggests that transfusions used to treat the anemia might not be the only cause of this toxicity." (PMID 31461451, 2019). "Indeed, BRCA1 and FANCA (a member of the Fanconi Anemia family of proteins) are involved in detecting DNA damage, causing cell cycle arrest and allowing DNA repair, which contributes to chemoresistance, while disruption of the BRCA1 pathway may promote sensitivity to platinum-based therapies." (PMID 18302766, 2008).
ovarian carcinoma (17 papers, 2005 to 2025). A malignant neoplasm originating from the surface ovarian epithelium. "In another study involving 1,021 hereditary cancer patients, 35 pathogenic variants were identified across eight genes, with FANCA emerging as the most frequently mutated FA gene in both breast cancer/breast and ovarian cancer cases." (PMID 39421870, 2024). "The researchers found that carriers of FANCA mutations were significantly associated with breast and ovarian cancer risks." (PMID 32762026, 2020). "In contrast, in spontaneous ovarian cancers FANCA mutations are rare, with both germline and somatic mutations in BRCA1/2 occurring far more frequently than any other FA genes." (PMID 36046263, 2020). "FANCA gene DNA repair gene associated with autosomal recessive Fanconi anemia type A, and there is some preliminary evidence of the association of monoallelic pathogenic variants in FANCA and Hereditary Breast and Ovarian Cancer and prostate cancer." (PMID 35085295, 2022). "Loss of FANCA function is associated with hereditary breast and ovarian cancer." (PMID 31931827, 2020). "FANCA is also a potential breast and ovarian cancer susceptibility gene." (PMID 15860134, 2005). "In the ovarian cancer cell lines A2780/4OHP and A2780/cOHP the highest increase was observed for FANCA." (PMID 31344863, 2019). "Significant deletions were observed in regions such as 5q11-13, frequently reported as loss of heterozygosity (LOH) in ovarian cancer, 8p23 encoding DBC1 (deleted in breast cancer 1 gene), 10p24 harboring PTEN, 16q24 encoding CDH1 (E-cadherin) and FANCA, and 19q13.3 encompassing STK11 (LKB1)." (PMID 40953111, 2025). "A role for FANCA is well characterized in ovarian cancer chemoresistance." (PMID 36046263, 2020). "The results showed that FANCA expression was higher in stage I ovarian cancer than in stage III." (PMID 32762026, 2020). "Other HRR pathway-related genes (ATM, ATR, CDK12, FANCA, FANCD2 and RAD50) were also found to play an essential role in ovarian cancer pathogenesis." (PMID 36729997, 2022).
prostate carcinoma (16 papers, 2015 to 2025). A carcinoma that arises from epithelial cells of the prostate gland. "FANCA-associated DNA repair mutations occur more frequently in prostate cancer with high Gleason grade as compared to the low Gleason grade, and the prognosis is generally worse." (PMID 35042833, 2022). "The loss of FANCA function in the germline is considered to be a pathogenic mutation in the development of prostate cancer." (PMID 35042833, 2022). "We present a case of prostate cancer that was resistant to second-generation antiandrogens and taxanes and showed somatic loss of the homologous recombination repair gene FANCA." (PMID 31931827, 2020). "A previous study reported that the prevalence of DNA repair mutation involving FANCA was higher in prostate cancer cases with high Gleason grade groups than in cases with low Gleason grade groups." (PMID 31931827, 2020). "While germline loss of FANCA function is known as a causative variant for prostate cancer development, it has also been reported that somatic variants in DNA repair genes, including FANCA, are increased in metastatic CRPC tissue." (PMID 31931827, 2020). "In prostate cancer cells, FANCA knockout is associated with hypersensitivity to cisplatin." (PMID 31931827, 2020). "Furthermore, loss of FANCA is associated with a familial history of prostate cancer." (PMID 31931827, 2020). "BAP1 alterations stood out in kidney (9.9%) and cervix (2.9%) cancers, with ATM most frequent in bladder cancer (7.7%), CDK12 notable in prostate cancer (7.4%), and FANCA prominent in melanoma (3.1%)." (PMID 40420266, 2025). "For prostate cancer subtypes, the most frequently mutated genes are BRCA2/FANCD1 at 54.5% and FANCA at 12%, both in prostate small cell carcinoma." (PMID 39421870, 2024). "Homozygous deletions of the FANCA gene occur in about 6% of prostate cancers, according to some studies." (PMID 36998466, 2023). "In vitro prostate cancer cells with FANCA deletions seem to have higher sensitivity to cisplatin and other DNA damaging substances compared to cells with wild-type FANCA." (PMID 36998466, 2023). "The National Comprehensive Cancer Network prostate cancer guideline recommends genetic counseling for patients with prostate cancer and having BRCA1/2, ATM, PALB2, or FANCA mutation." (PMID 31931827, 2020). "Whereas this mutation has been reported in prostate cancer and is predicted to be pathogenic, its impact on FANCA function has not been directly assessed." (PMID 40111122, 2025). "We describe a case of aggressive, castration-resistant prostate cancer with FANCA homodeletion." (PMID 31931827, 2020). "Additionally, CDK12 (17.6%) and FANCA (11.8%) also played significant roles in prostate cancer." (PMID 40420266, 2025). "Interestingly, several variants were observed in genes that have not been well characterized in patients with prostate cancer, including the tumor suppressor gene FANCA as well as WRN, which is associated with the premature aging disease Werner's syndrome." (PMID 36446039, 2022). "Importantly, the HRR abnormalities are observed in 31% of advanced prostate cancers and include: BRCA2 (9.8%), CDK12 (5.6%), ATM (5.2%), CHEK2 (1.8%), BRCA1 (1.4%) FANCA (1.3%), and ATR (1.1%)." (PMID 31366128, 2019).
melanoma (13 papers, 2007 to 2025). A malignant, usually aggressive tumor composed of atypical, neoplastic melanocytes. "Germline coding variations and single-nucleotide polymorphism of the FANCA gene have been associated with melanoma susceptibility and overall patient survival, respectively." (PMID 35883549, 2022). "Alternatively, the effect of FANCA deficiency in melanoma cells could have a less severe effect in term of senescence and ROS production than FANCD2 depletion." (PMID 27827420, 2016). "Additionally, common variants at the FANCA gene have been suggested to predict melanoma survival." (PMID 29739929, 2018). "For example, genes in cluster 2 (SPIRE2, SPATA2L), 3 (OCA2, DBNDD1, FANCA, GAS8) and 4 (URAHP, DEF8, CPNE7, MC1R) underlie the associations between melanoma and pigmentation traits." (PMID 38308491, 2024). "Another recent analysis of human melanoma found that 21.4% of this tumor type has at least one HRD gene mutation including BRCA1, ARID1A, ATM, ATR and FANCA." (PMID 34885093, 2021). "Specifically, less than 10% of exponentially growing melanoma cells displayed more than five 53BP1 foci per nucleus, a percentage that exceeded 60% when MiTF, FANCA or FANCD2 were silenced individually." (PMID 27827420, 2016). "In line with a crosstalk between MiTF and the FANC pathway, MiTF silencing in melanoma cells triggered a strong reduction in the mRNA level of 4 analysed FANC genes: FANCA, FANCD2, FANCC and FANCG." (PMID 27827420, 2016). "Notably, several consequences of MiTF depletion in melanoma were recapitulated by FANCA or FANCD2 depletion despite the maintenance of MiTF expression; inversely, their overexpression limits the consequence of MiTF depletion on melanoma cell behaviour." (PMID 33723374, 2021). "Moreover, FANCA or FANCD2 knockdown dramatically reduced the migration ability of the melanoma cells and suppressed their capacity to sustain anchorage-independent cell growth, which are indicators of tumorigenicity and invasiveness." (PMID 27827420, 2016). "To validate that increased DNA damage and cellular senescence in MiTF-silenced melanoma cells relied directly on the downregulation of the FANC pathway, we carried out experiments involving the forced expression of FANCA or FANCD2." (PMID 27827420, 2016). "FANCA and FANCL mRNAs were clearly upregulated in E2F1 overexpressed SKMEL-2 melanoma cells, whereas FANCD1 and FANCG mRNAs were unchanged after E2F1 overexpression." (PMID 19936073, 2007). "It is noteworthy that silencing of FANCD2 in melanoma cells recapitulates all the key cellular phenotypes of FA cells while FANCA depletion fails to induce a significant increase in the intracellular level of ROS." (PMID 27827420, 2016). "The forced expression of FANCA or FANCD2 in MiTF-depleted cells significantly reduced the occurrence of spontaneous DNA damage, as indicated by γH2AX and 53BP1 foci formation and foster melanoma cell proliferation in response to MMC exposure." (PMID 27827420, 2016). "In addition, databases deposited in NCBI revealed that FANCA, FANCL, and probably FANCC genes were upregulated in E2F1-overexpressed SKMEL-2 melanoma cells." (PMID 19936073, 2007). "Moreover, MiTF-depleted cells presented a cellular and chromosomal hypersensitivity to ICL-inducing agents similar to that reported in FANCA- or FANCD2-depleted melanoma cells (e and data not shown)." (PMID 27827420, 2016). "Eight of them had not been detected by routine testing (FANCA p.W911Dfs*31 in GE02 pancreatic cfDNA, 3 NRAS p.Q61K in GE17 and GE15 melanoma and in GE11 cholangiocarcinoma, a NRAS p.G13D in GE22 pancreatic cancer, an IDH2 p.R172S in GE11 cholangiocarcinoma, and an IDH2 p.R140Q in GE14 melanoma)." (PMID 38750555, 2024).
bone marrow failure (12 papers, 2005 to 2025). "Another important finding, as far as the correlation between genotype and phenotype is concerned, was that patient 3, who was classified within the FA-E complementation group, demonstrated the earliest onset of bone marrow failure when compared to patients harbouring mutations in the FANCA gene." (PMID 40868424, 2025). "FANCA protects humans from bone marrow failure and malignancies by maintaining genomic integrity." (PMID 25953249, 2015). "Similarly, patients with hypomorphic variants in FANCA, the most commonly diagnosed FA disease–associated gene, might present later in life with cancer and infertility but no developmental abnormalities or bone marrow failure." (PMID 40244696, 2025). "Since others have previously also documented successful HDR gene editing strategies to repair or compensate defects in FANCA, FANCC, FANCD1/BRCA2 and FANCI, the combined data support that gene editing can be a promising therapeutic strategy to prevent onset of bone marrow failure in FA patients." (PMID 30683899, 2019).
leukemia (6 papers, 2015 to 2025). A malignant (clonal) hematologic disorder, involving hematopoietic stem cells and characterized by the presence of primitive or atypical myeloid or lymphoid cells in the bone marrow and the blood. "FANCA deficiency has been linked to increased tumorigenicity and poor prognosis of leukemia." (PMID 41303409, 2025). "Additionally, FANCA loss of function in leukaemic SPI1-overexpressing cells deregulates a complex network of genes known for their strong association with leukaemia development." (PMID 37573408, 2023). "In our study, we found NOTCH2, FANCA, BCR, and ROS1 were significantly mutated in 109 Chinese patients with leukemia." (PMID 32638549, 2020). "Mutational analysis was used to map the genetic variants in leukemia, and found that the highest mutations occurred in PDE4DIP, followed by NOTCH2, FANCA, BCR, and ROS1 in almost all leukemia patients." (PMID 32638549, 2020). "Depletion of FANCA in TgSpi1 mice leads to progression from preleukaemia to leukaemia without increasing mutation load." (PMID 37573408, 2023). "Taken together, these results suggest that concomitant inheritance of rare variants in FANCA, FANCP/SLX4 and GEN1 on the specific genetic background of this familial case, could lead to increased genomic instability, hematopoietic dysfunction, and higher risk of childhood leukemia." (PMID 26201965, 2015). "Previously, NOTCH2, FANCA, BCR, and ROS1 have been described to play an important role in leukemia." (PMID 32638549, 2020).
lung carcinoma (6 papers, 2016 to 2025). "CRISPR-mediated FANCA-knockout in the lung cancer cell line models A549 and H1299 also sensitized cells to PARPi, demonstrating that FANCA deficiency induces synthetic lethality across multiple cancer types." (PMID 40630542, 2025). "Furthermore, DDR mutations, such as ATM, PTEN, MRE11, and FANCA mutations, have been found in a large proportion of lung cancer patients, as well as BRCA1/2 mutations in 5% of patients, justifying the administration of PARP inhibitors to lung cancer patients." (PMID 37682974, 2023). "MMC treatment not only cross-links DNA but also inhibits expression of SPTAN1 through miR-128-3p to disrupt recruitment of DNA repair-associated proteins (FANCA and XPF), with dual destructive effects in lung cancer cells." (PMID 28938540, 2017). "Here, we demonstrate that overexpression of miR-128-3p down-regulates SPTAN1 expression via translational repression and results in the failure to recruit FANCA and XPF to facilitate chromosomal instability after MMC-induced DNA ICL damage in lung cancer cells." (PMID 28938540, 2017).
acute myeloid leukemia (5 papers, 2012 to 2023). Acute myeloid leukemia (AML) is a group of neoplasms arising from precursor cells committed to the myeloid cell-line differentiation. "Concerning the hematologic phenotype, patients with FANCG PV have been found to have more severe cytopenia as well as a higher frequency and an earlier diagnosis of acute myeloid leukemia or myelodysplastic syndrome than patients with FANCA or FANCC genotypes." (PMID 35216452, 2022). "Since FA patients display a high risk of childhood acute myeloid leukemia (AML), we stably knocked down FANCA in the AML cell line THP‐1 to assess sensitivity to SIK2 inhibition in a relevant cancer type." (PMID 34058059, 2022). "FANCA dysfunction might promote cytogenetic instability in adult acute myelogenous leukemia." (PMID 32638549, 2020).
osteosarcoma (5 papers, 2020 to 2024). A usually aggressive malignant bone-forming mesenchymal neoplasm, predominantly affecting adolescents and young adults.
pancreatic cancer (5 papers, 2020 to 2025). "The report pointed out that FANCG and FANCA heterozygous mutations were susceptible to haematological malignancies and pancreatic cancer." (PMID 32762026, 2020). "High expression of FANCA and FEN1 is associated with poor prognosis in pancreatic cancer." (PMID 40847617, 2025).
diffuse large B-cell lymphoma (4 papers, 2020 to 2025). "Furthermore, the TET2/AID complex, which bound to the FA complementation group A (FANCA) promoter and induced its hypomethylation, facilitated oncogenic FANCA in diffuse large B cell lymphoma." (PMID 33029541, 2020). "Notably, AID facilitates TET2-mediated demethylation of the FANCA gene as a transcriptional cofactor in diffuse large B-cell lymphoma (DLBCL), while paradoxically collaborating with DNMT1 to maintain methylation at the BCL6 promoter." (PMID 40270606, 2025). "In diffuse large B-cell lymphoma (DLBCL) cell lines, AID cooperates with the TET enzyme TET2 to demethylate Fanconi anemia complementation group A (FANCA), increasing its expression." (PMID 39280246, 2024).